SDE2 (spliceosome associated SDE2)
Description:
Inhibits translesion DNA synthesis by preventing monoubiquitination of PCNA, this is necessary to counteract damage due to ultraviolet light-induced replication stress. SDE2 is cleaved following PCNA binding, and its complete degradation is necessary to allow S-phase progression following DNA damage. Plays a role in pre-mRNA splicing by facilitating excision of relatively short introns featuring weak 3'-splice sites (ss) and high GC content. May recruit CACTIN to the spliceosome (By similarity). Plays a role in ribosome biogenesis by enabling SNORD3- and SNORD118-dependent cleavage of the 47S rRNA precursor. Binds ncRNA (non-coding RNA) including the snoRNAs SNORD3 and SNORD118.
Synonyms: C1orf55; FLJ35382; dJ671D7.1
Tractability: Small molecule: a structure with a bound ligand is known. Antibody: its Gene Ontology location is reachable by antibodies, with high confidence; the Human Protein Atlas places it where antibodies can reach. PROTAC: UniProt records ubiquitination sites on it; ubiquitination databases record sites on it; its protein half-life has been measured.
Gene: Protein-coding gene on chromosome 1 (225,982,702 to 225,999,350, reverse strand). Ensembl gene ENSG00000143751.
Subcellular location: Nucleus; Cytoplasm
Subcellular location (Human Protein Atlas): Nuclear speckles; Cytosol; Golgi apparatus; Plasma membrane
Pathways (Reactome):
Metabolism of RNA: mRNA Splicing - Major Pathway
Gene Ontology:
Molecular function: damaged DNA binding; protein binding; snoRNA binding
Biological process: cellular response to UV; endonucleolytic cleavage of tricistronic rRNA transcript (SSU-rRNA, 5.8S rRNA, LSU-rRNA); mitotic G1 DNA damage checkpoint signaling; mRNA cis splicing, via spliceosome; protein processing; protein ubiquitination
Cellular component: cytoplasm; cytosol; mitochondrion; nuclear speck; nucleus; plasma membrane; nucleoplasm
Genetic constraint (gnomAD): Loss-of-function variants: 20 observed, 29.19 expected, observed/expected ratio (o/e) 0.69, 90% interval 0.48 to 1. The upper end of that interval is the gene's LOEUF score, 1, which puts it in group 4 of 6, group 1 being the genes least tolerant of losing a copy. Missense variants: 414 observed, 449 expected, observed/expected ratio (o/e) 0.92, 90% interval 0.85 to 1. Synonymous variants: 164 observed, 169.48 expected, observed/expected ratio (o/e) 0.97, 90% interval 0.85 to 1.1.
Homologues: Orthologues: chimpanzee SDE2 (99% identical), macaque SDE2 (94% identical), rabbit SDE2 (75% identical), pig SDE2 (74% identical), guinea pig SDE2 (71% identical), dog SDE2 (69% identical), mouse Sde2 (67% identical), rat Sde2 (66% identical), tropical clawed frog sde2 (47% identical), zebrafish sde2 (42% identical), Caenorhabditis elegans sde-2 (24% identical), Drosophila melanogaster CG5986 (19% identical). Paralogues in human: SF3A3 (17% identical).
Diseases named in the same sentence as SDE2 in open-access papers:
SDE2 is named in the same sentence as 8 diseases in open-access papers, as found by Europe PMC text mining. Sharing a sentence is not in itself a finding about the gene and the disease. The quoted sentences say what the papers report.
breast carcinoma (1 paper, 2021). "Low mRNA expression levels of SDE2 gene were significantly associated (P = 0.01) with poorer breast cancer survival, while, in contrast, high expression of H3F3A was associated with lower survival (P = 6.7 × 10−5)." (PMID 34611289, 2021).
prostate carcinoma (1 paper, 2021). A carcinoma that arises from epithelial cells of the prostate gland. "The functional roles of SDE2 have been studied in a proteome dynamics analysis in prostate cancer cells; the results suggested that alterations of the gene might diminish the error-prone DNA repair pathway activation and promote missense mutations." (PMID 34611289, 2021).
tumor (3 papers, 2021 to 2026). "Depletion of SDE2 enhanced cellular sensitivity to DNA damage and suppressed tumor growth, suggesting that SDE2 may be a potential therapeutic target for hypoxic tumors." (PMID 33796526, 2021). "Targeting SDE2 restores ATG5-dependent autophagy, activates ferroptosis, and inhibits tumor growth." (PMID 41666676, 2026).
cancer (1 paper, 2016). A tumor composed of atypical neoplastic, often pleomorphic cells that invade other tissues. "Knowledge on such mechanism will be useful to identify novel cancer therapeutic interventions exploiting deregulated ubiquitin signaling and SDE2 activities in cancer." (PMID 27906959, 2016).
SDE2 also shares sentences with these, for which no sentence is quoted: Sepsis (2 papers); breast tumors (1); multiple myeloma (1); Obesity (1).